RAB38 (RAB38, member RAS oncogene family)
Diseases named in the same sentence as RAB38 in open-access papers (continued):
Sharing a sentence is not in itself a finding about the gene and the disease.
glioblastoma (1 paper, 2021). The most malignant astrocytic tumor (WHO grade IV). "It has been established that RAB38 is upregulated in glioblastoma and associated with a poor prognosis and enhanced cell migration." (PMID 34209035, 2021). "Consistently, rescue experiments demonstrated that loss of RAB38 causes a reduction in glioblastoma viability through downregulation of Bcl-xL." (PMID 34209035, 2021). "In summary, we have shown that RAB38 is implicated in mediating glioblastoma growth and resistance to cell death and that this occurs by modulation of distinct cellular pathways." (PMID 34209035, 2021). "Although the mechanisms by which statins cause glioblastoma cell death are likely multiple, our hypothesis is that statin inhibition of RAB38 prenylation may be one element mediating their glioblastoma cytotoxic action." (PMID 34209035, 2021). "Here, we examine the effects of loss of RAB38 function in human glioblastoma cell cultures." (PMID 34209035, 2021). "Our studies demonstrated that treatment of glioblastoma cells with simvastatin or lovastatin causes a dose-dependent decrease in RAB38 expression and cell viability in LN229, T98G, and GBM43 cells in vitro, which to the best of our knowledge has not been reported previously." (PMID 34209035, 2021). "RAB38, also known as rrGTPbp and NY-MEL-1, has been reported to be upregulated in glioblastoma, and high levels of its expression are associated with a poor prognosis and enhanced cell migration." (PMID 34209035, 2021). "All glioblastoma cell lines in this study showed RAB38 protein expression, albeit at different levels." (PMID 34209035, 2021). "In summary, our findings suggest that RAB38 is a potential therapeutic target for glioblastoma treatment." (PMID 34209035, 2021). "In conclusion, our study demonstrates that RAB38 is a critical regulator of cell survival in glioblastoma in vitro and strongly indicates RAB38 as a potential therapeutic target singly or in combination therapies for glioblastoma treatment." (PMID 34209035, 2021). "We performed extracellular flux analysis to determine if there were changes in metabolic activity of glioblastoma cells following RAB38 knockdown." (PMID 34209035, 2021). "To gain insight into the pathways affected by RAB38 activity in the context of glioblastoma, we focused our attention on c-Myc, a transcriptional factor that plays an important role in the pathogenesis of many tumors, including glioblastoma." (PMID 34209035, 2021). "Taken together, our data suggest that Bcl-xL is likely involved in the cell death induced by RAB38 silencing and protects glioblastoma cell lines from cell death." (PMID 34209035, 2021). "The goal of this study was to investigate if RAB38 affects glioblastoma cell survival and proliferation and can present as a novel therapeutic target for glioblastoma." (PMID 34209035, 2021). "We found that genetic interference of RAB38 resulted in a decrease in glioblastoma growth through inhibition of proliferation and cell death induction." (PMID 34209035, 2021). "The results confirm that the RAB38 protein is expressed in glioblastoma cells, reinforcing the notion that RAB38 is a viable, potential therapeutic target for glioblastoma." (PMID 34209035, 2021). "Taken together, these results suggest that RAB38 regulates the cell cycle of glioblastoma cells in part through c-Myc." (PMID 34209035, 2021). "This study suggests RAB38 is an important regulator of glioblastoma cell viability." (PMID 34209035, 2021). "To determine if RAB38 could play a potential role in regulating glioblastoma cell death and survival, we examined the effects of RAB38 silencing on the human glioblastoma established cell lines LN229 and T98G and on the patient-derived cell line GBM43." (PMID 34209035, 2021). "Furthermore, in glioblastoma cell lines, a significant reduction in cell cycle progression induced by RAB38 knockdown and an increase in cell death were demonstrated." (PMID 34209035, 2021).
glioblastoma (continued). "Significant decreases in the oxygen consumption rate and glycolytic activity suggest that RAB38 may regulate mitochondrial-mediated cell death in glioblastoma." (PMID 34209035, 2021). "In total, these observations suggest that RAB38 may be particularly sensitive to prenylation inhibition and, thus, be a target for in vivo glioblastoma therapy." (PMID 34209035, 2021). "To determine if RAB38 could be a selective therapeutic target for glioblastoma cells, we examined the effects of RAB38 silencing on astrocytes isolated from human cerebral cortex." (PMID 34209035, 2021). "We test the overarching hypothesis that RAB38 plays an important prosurvival role in glioblastoma cells." (PMID 34209035, 2021). "Here, we test the hypothesis that RAB38 regulates glioblastoma growth using human glioblastoma cell lines." (PMID 34209035, 2021). "In our studies, we found that human astrocytes and our panel of glioblastoma cultures demonstrated RAB38 protein expression (data not shown)." (PMID 34209035, 2021). "From our currently available data, it appears most likely that RAB38 silencing is sufficient to induce cell death in glioblastoma cell lines but RAB38 suppression is not necessary for the killing effects of statins." (PMID 34209035, 2021). "Glioblastoma cell viability 14 days following transfection of RAB38 siRNA was significantly decreased compared to nontargeting siRNA controls." (PMID 34209035, 2021).
leprosy (1 paper, 2021). Leprosy is a chronic infectious disease affecting primarily the skin and peripheral nervous system. "RAB32 and RAB38 have been shown to mediate phagosome restriction of intracellular pathogens, notably Mycobacterium leprae, the causative agent of leprosy." (PMID 34397087, 2021).
lung disease (1 paper, 2018). "Growing evidence suggests that Rab38 is an additional candidate gene for the lung disease in human HPS." (PMID 30060521, 2018).
malaria (1 paper, 2012). Malaria is a serious and sometimes fatal disease caused by a parasite that commonly infects a certain type of mosquito which feeds on humans. "The results showed that, compared to the negative control, the live malaria parasite was able to induce an increase in the expression of Rab1a, Rab1b, Rab7a, Rab10, Rab14, Rab20, Rab27a, Rab32 and Rab38." (PMID 22911692, 2012).
osteoporosis (1 paper, 2023). A condition of reduced bone mass, with decreased cortical thickness and a decrease in the number and size of the trabeculae of cancellous bone (but normal chemical composition), resulting in increased fracture incidence. "Our results indicate that both Rab32 and Rab38 may serve as drug targets for suppressing osteoclast function and may be developed like a bisphosphonate or like odanacatib, a CTSK inhibitor, as a therapeutic agent for rheumatoid arthritis, osteoporosis, and periodontitis." (PMID 37793839, 2023).
pancreatic adenocarcinoma (1 paper, 2022). "As a member of RAB family, the cancer promoting effects of RAB38 has been verified in pancreatic cancer, since RAB38 was correlated with progression in patients with pancreatic adenocarcinoma." (PMID 36249755, 2022).
pancreatic cancer (1 paper, 2022). "And downregulation of RAB38 could suppressed the proliferation and migration of pancreatic cancer cells." (PMID 36249755, 2022).
retinal degeneration (1 paper, 2010). Degeneration of the retina. "Neuronal dysfunction is caused by abnormalities in Rab1 and Rab7; retinal degeneration is caused by abnormalities in Rab8; and both immune and pigmentation disorders are caused by abnormalities in Rab27 and Rab38." (PMID 21143914, 2010).
cancer (5 papers, 2010 to 2022). A tumor composed of atypical neoplastic, often pleomorphic cells that invade other tissues. "For example, for samples expressing transcript asm¦33042290, mRNA expression of RAB38, the predicted adjacent gene, was higher in cancer but in not normal samples (Fig4B)." (PMID 26253570, 2015).
tumor (4 papers, 2018 to 2024). "RAB38 regulates intracellular vesicular trafficking and some researchers have found that RAB38 may be an important prognostic factor in NSCLC, and serve a critical role in NSCLC-associated tumor metastasis." (PMID 32038235, 2019).
infection (3 papers, 2012 to 2024). The state of being infected such as from the introduction of a foreign agent such as serum, vaccine, antigenic substance or organism. "In contrast, Ad-Rab38-infected cells expressed Rab38 protein (molecular weight ~ 26 kDa) by 24 h after infection." (PMID 28438206, 2017).
RAB38 also shares sentences with these, for which no sentence is quoted: asthma (1 paper); astrocytomas (1); breast carcinoma (1); colorectal cancer (1); frontotemporal lobar degeneration (1); gastrointestinal disorders (1); lung carcinoma (1); metastatic melanoma (1); myeloproliferative diseases (1); Nephropathy (1); ovarian carcinoma (1); periodontitis (1); psychiatric disorder (1); pulmonary fibrosis (1); renal cell carcinoma (1); rheumatoid arthritis (1); schizophrenia (1).